EDN1 (endothelin 1)
Diseases named in the same sentence as EDN1 in open-access papers (continued):
Sharing a sentence is not in itself a finding about the gene and the disease.
tumor (continued). "We show that SOX4 directly regulates endothelin-1 (ET-1) expression and can thereby promote tumor-induced angiogenesis both in vitro and in vivo." (PMID 30507376, 2018). "In accordance, studies show that endothelin-1 is important for myogenic tone development in tumor arterioles." (PMID 29566737, 2018). "Endothelin-1 (ET-1) is involved in the pathogenesis of cardiac and renal diseases, and in the progression of tumour growth in cancer, but current diagnosis and treatment remain inadequate." (PMID 28694457, 2017). "END 1 (Endothelin 1) can induce tumor protease activation and enhance migration and invasion of OVCA433 cells." (PMID 28077802, 2017). "Correlation of Endothelin-1 expression in needle biopsy specimens in expected with extra-prostatic extension of tumor in radical prostatectomy specimens, perineurial invasion and serum PSA level at the time of diagnosis." (PMID 29515640, 2017). "EDN1 expression is enhanced in tumours of patients on treatment and confers drug resistance through ERK re‐activation in a paracrine manner." (PMID 28606996, 2017). "This was intriguing as it suggested that BQ788, despite enabling MITF up‐expression in the presence of BRAF inhibitor, had suppressed EDN1 expression within the tumours." (PMID 28606996, 2017). "Our data support the existence of autocrine and paracrine signals and implicate for a role of PDGF-C, -D and EDN1 signaling in GBM tumor growth." (PMID 27344175, 2016). "A decrease in BC cell adhesion and tumor growth in vivo following PFN downregulation are observed, likely associated with the concomitant downregulation of Fibronectin receptor, Endothelin-1, and Actin polymerization." (PMID 27683119, 2016). "Further analysis revealed that daily administration of anakinra significantly reduced endothelin 1 gene expression in both mouse bone and human tumours." (PMID 27765923, 2016). "ILK expression was shown to be enhanced downstream of endothelin-1/endothelin A receptor signaling and inhibition of this signaling axis reduced tumor growth." (PMID 26959113, 2016). "Endothelin-1 (ET-1) autocrine and paracrine signaling modulate cell proliferation of tumor cells by activating its receptors, endothelin A receptor (ETAR) and endothelin B receptor (ETBR)." (PMID 27490540, 2016). "A family of proteins involved in tumor progression are the endothelins which include endothelin-1, 2 and 3 (ET-1, ET-2 and ET-3)." (PMID 26225957, 2015). "We further investigated tumor neovascularization by immunostaining for endothelin-1, an endothelial-specific marker." (PMID 25419563, 2014). "Endothelin-1 (ET-1), which promotes tumor cell proliferation and survival through the endothelin A receptor (ETAR), is expressed in a range of malignancies." (PMID 23426781, 2013). "Endothelin-1 (ET-1) is expressed in a variety of malignancies, and promotes tumor cell proliferation and survival through the ET A receptor (ETAR)." (PMID 23420812, 2013). "EDN1 is also known to have effects on the growth and progression of various tumor types by affecting proliferation and resistance to apoptosis." (PMID 23206527, 2012). "Endothelin-1 (ET-1) acting through the endothelin A (ETA) receptor is believed to promote tumour proliferation, angiogenesis, migration and invasion, as well as inhibiting apoptosis." (PMID 21414193, 2011). "Second, EDN1 and EDN2 binding to EDNRA can activate p125 focal adhesion kinase and paxillin, both of which have been associated with increased tumour cell invasion." (PMID 19527488, 2009). "Cross-talk between tumour and stromal cells can profoundly influence cancer cell invasion by increasing the availability of mitogenic peptides such as endothelin-1 (ET-1)." (PMID 18781169, 2008). "Activation of the endothelin A receptor (ETA) by endothelin-1 (ET-1) mediates events that regulate mitogenesis, apoptosis, angiogenesis and metastasis in tumours." (PMID 15956965, 2005).
tumor (continued). "There is accumulating evidence to suggest that endothelins, particularly endothelin-1 (ET-1), have a role in regulating the growth and proliferation of tumours." (PMID 15956965, 2005). "Importantly, the combinatorial inhibition of EDN1, in conjunction with oxaliplatin treatment, substantially enhances apoptosis and suppresses tumor growth both in vitro and in vivo." (PMID 41425720, 2025). "The role of endothelin-1 in tumor microcirculation and hypoxia adaptation also warrants further investigation, as its transient increase may have implications for vascular resistance and perfusion changes post-TACE." (PMID 40867270, 2025). "In osteoblastic bone metastasis, tumor cells release diverse elements, including endothelin-1 (ET-1), growth differentiation factor 15 (GDF15), and bone morphogenetic protein (BMP) which stimulate the proliferation and differentiation of osteoblasts principally via the Wnt signaling pathway." (PMID 38243240, 2024). "Endothelin-1 is a well-known growth factor secreted by tumor cells, regulating cellular processes through signaling via mitogen-activated protein kinase (MAPK), protein kinase B (Akt), integrin-linked kinase (ILK), and proto-oncogene tyrosine-protein kinase Src pathways." (PMID 36542159, 2023). "In addition, TGF-β induces the secretion of connective tissue growth factor, endothelin-1, and vascular endothelial growth factor, thus promoting the formation of a tumor metastatic microenvironment." (PMID 36776859, 2023). "Notably, endothelin-1 acts primarily through the ETA receptor and is implicated in the neoplastic growth of multiple tumor types." (PMID 37096326, 2023). "Except for fibroblasts, a total of 937 endothelial cells were also obtained, which were subclustered into five subsets, including extra-alveolar capillary ECs (Endo-C1; EDN1+), tumor ECs (Endo-C3; INSR+), and other ECs (Endo-C2, ICAM1+; Endo-C4, MAP1B+; Endo-C5, CXCR4+)." (PMID 36046337, 2022). "Together, after EDN1 was knocked down, the tumour load of mice was significantly reduced." (PMID 36053810, 2022). "Since endothelin-1 is one of the body’s most potent vasoconstrictors, it may regulate the perfusion of the tumor with leukocytes, which are found in the blood." (PMID 35203305, 2022). "These achievements put forward that EDN1 may be a potential target for anti-tumor growth and angiogenesis." (PMID 35896520, 2022). "In addition, the endothelin-1 (ET-1) axis contributes to the pathophysiology of several cancers by promoting tumor development and progression." (PMID 36009534, 2022). "To verify whether the angiogenic genes were involved in Roquin2-mediated tumor angiogenesis, we silenced EDN1 and PDGFC using shRNA lentiviruses in MDA-MB-231/shRoquin2 cells." (PMID 34345214, 2021). "The vasoconstrictive peptide Endothelin 1 (ET1), known for its direct effect on angiogenesis via VEGF and HIF1, is also associated with ICAM1 expression and the decreased presence of tumor infiltrating leukocytes (TIL)." (PMID 32974337, 2020). "To examine whether 419S1 and 420S1 can block tumor cell migration and proliferation, we injected 293T/EDN1 cells labelled with CM-Dil (red fluorescence) into 2 dpf embryonic yolk sacs of Tg(fli1:EGFP)." (PMID 31141996, 2019). "Studies have revealed that E. purpurea crude polysaccharides at 100 μg can significantly stimulate macrophages to kill P815 tumor cells, improve the macrophage production of interleukin level of endothelin 1 (IL-1), and stimulate the proliferation of B lymphocytes in mice." (PMID 30105254, 2018). "Endothelin-1 regulates neovascularization by controlling endothelial cell migration, proliferation, and invasion as well as induction of micro-vessel density and production of vascular endothelial growth factor in tumor cells." (PMID 29515640, 2017).
tumor (continued). "Overall our data lead to a model, whereby in tumours on treatment with BRAF inhibitor‐induced MITF up‐expression in MITF‐high cells increases intra‐tumour EDN1 levels, which can act on MITF‐high (paracrine or autocrine) as well as AXL‐high cells to re‐activate ERK." (PMID 28606996, 2017). "Moreover, the fibrosis and metastasis related genes and tumor markers were also analyzed in three independent 11 month-old edn1 transgenic fish to confirm the presence of hyperplasia and HCC." (PMID 24416389, 2014). "The up-regulation of cell cycle/proliferation-related genes, tumor markers, and metastasis markers detected at 11 months of age in the edn1 transgenic fish was also in accord with the observation that at this age edn1 overexpression caused hyperplasia and HCC in zebrafish." (PMID 24416389, 2014). "Additionally, we examined the data set by using the Gene Expression Omnibus website to determine the EDN1 mRNA levels in tumors and non-tumor samples." (PMID 24416389, 2014). "EDN1 has been found to enhance tumor growth by promoting angiogenesis." (PMID 24416389, 2014). "Tumor cells disturb the balance of osteoblast and osteoclast activity by secretion of bone-active regulatory factors such as endothelin-1 (ET1), interleukin-6 (IL6) and transforming growth factor β (TGFβ) in order to enhance bone turnover and release of nutrients and growth factors." (PMID 23792785, 2013). "EDN1, which is a hypoxia-inducible angiogenic growth factor for surrounding epithelial and endothelial cells, plays an important role in cancer-stromal interactions and tumor progression, and its expression is related to poor prognosis in NSCLC." (PMID 20628618, 2010). "In addition, this study demonstrated that knockdown of LSR could increase the expression of pro-oncogenic genes, such as interleukin 1 alpha and endothelin 1, which could contribute to tumor initiation and progression." (PMID 35586495, 2022). "Endothelin-1 acts through different signaling pathways and is involved in normal cell functions as well as those contributing to cancer development and progression, including cell proliferation, reduced apoptosis, epithelial mesenchymal transition, invasion, metastasis, and tumor angiogenesis." (PMID 32194414, 2020). "However, tumour cells may produce factors that inhibit osteoclast activity [endothelin-1 (ET-1), OPG], leading to the formation of osteoblastic or mixed lesions." (PMID 27761364, 2016). "Previous studies have revealed that EDN1 may also affect tumor invasion and metastasis." (PMID 24416389, 2014). "Algogens released from a tumor or its surrounding tissue and transported all over the body, such as endothelin-1, prostaglandins and ATP, may directly or indirectly sensitize and/or excite primary afferent nociceptors and therefore interact with the proteins that regulate Nav1.8." (PMID 20482896, 2010). "Endothelin-1 may also facilitate tumour growth through the promotion of angiogenesis." (PMID 12610497, 2003). "Between ARGs_High tumour cells and T cells, ITGB2-ICAM1 and TGFB1-TGFBR1 were ligand-receptor pairs with strong regulatory potential, while EDN1, JUNB, SOCS3, VIM and COL1A2 were top genes target to TGFB1." (PMID 40830065, 2025). "Collectively, these results identify EDN1 as a context-dependent oncogene that is selectively upregulated in CRC and drives tumor progression through proliferation and apoptosis resistance." (PMID 41425720, 2025). "Recent evidence highlights the role of Endothelin-1 (ET1), a bioactive peptide, in promoting tumor aggressiveness through activation of its receptors (ETRs)." (PMID 40830989, 2025). "BDKRB2 can promote angiogenesis by increasing vascular permeability and upregulating vascular endothelial growth factor (VEGF) and can also promote tumor cell migration and invasion through TRPM7, MMP2, endothelin-1, and ERK signaling pathways." (PMID 40224547, 2025).
tumor (continued). "Other studies clarify that tumor-derived growth factors VEGF and endothelin-1 inhibit the expression of adhesion molecules and immobilize T cells into tumors." (PMID 38887558, 2024). "Furthermore, in cluster 5, the upregulation of the endothelin receptor A (EDNRA) gene may have enhanced the pleiotropic effects of its ligand, endothelin-1, which is known to regulate EMT, angiogenesis, and immune response and has been implicated in drug resistance in various tumor types." (PMID 38999963, 2024). "In this context, within the G-protein coupled receptor (GPCR) family, the endothelin-1 has a critical role in HG-SOC progression, by controlling different tumour-promoting effects via the receptors ETA (ETAR), and ETB (ETBR)." (PMID 39503511, 2024). "Confirming the role of tumor-derived EDN1 in facilitating immune evasion, Edn1−/− KPAR tumors grew slower than parental tumors specifically in immunocompetent mice." (PMID 38635884, 2024). "EDNRA regulates its own expression and that of EDN1 through the STAT3 signalling pathway, creating a positive feedback loop that promotes tumour growth and metastasis." (PMID 39601333, 2024). "Results showed that the regulatory factors CRNDE, EDN1, JUNB, and MAP2K1/2, ZFP36 mainly regulate differentially expressed genes (VEGFA, EGFR, PLAUR) to regulate invasion of cells, invasion of tumor, and microtubule dynamics." (PMID 38711992, 2024). "IL-6 released from MSCs stimulates the release of endothelin-1 (ET-1) in cancer cells, which in turn triggers the activation of Akt and ERK in endothelial cells, improving their ability to attract other cells to the tumor and promoting angiogenesis." (PMID 38022534, 2023). "Deletion of the IL30 gene in PC cells inhibits endothelial expression of IGF1, EDN1, ANG and CXCL10 and substantially impairs tumor angiogenesis." (PMID 38087324, 2023). "Subsequently, protein levels of CycA, EDN1, CLDN1, and pro-apoptotic proteins (Caspase-3 and Bax) in tumor tissues were detected by western blot." (PMID 38105218, 2023). "MSC-derived IL-6 induces endothelin-1 (ET-1) secretion from cancer cells, which activates the AKT and ERK pathways in endothelial cells to promote endothelial cell recruitment and tumor neovascularization in gastrointestinal cancer cells." (PMID 37189649, 2023). "Identification of new therapeutic targets is crucial, and recent studies have shown that the Endothelin-1 (ET-1) signaling pathway, involving ETAR and/or ETBR receptors (ETRs), plays a crucial role in promoting tumor aggressiveness in various cancer models." (PMID 38072958, 2023). "Within the microenvironment of solid tumors, such as GBC, various autocrine and paracrine signaling molecules enhance tumor malignancy, among them Tumor Necrosis Factor-alpha (TNFα), Vascular Endothelial Growth Factor (VEGF), and Endothelin-1 (ET-1)." (PMID 38072958, 2023). "Elevated ARHGEF2 accelerates angiogenesis by modulating mRNA and the protein expression levels of EDN1, promoting HCC cell proliferation and tumor formation both in vitro and in vivo." (PMID 35896520, 2022). "In this study, YAP and TEAD1 are co-localized at the promoter regions of CTGF (CCCTC-Binding Factor), MYC, EDN1 (Endothelin 1), and EDN2, leading to cancer cell proliferation and migration in vitro as well as tumor growth in xenograft model." (PMID 35602596, 2022). "Elevated ARHGEF2 accelerates HCC angiogenesis via the EDN1 pathway, enhances HCC cell proliferation and tumor growth both in vitro and in vivo, and contributes to ER stress-related treatment resistance." (PMID 35896520, 2022). "Analysing the xenografted CRPC tumours from mice reveals that mice treated with AA downregulates the expression of the angiogenic promoting factors ANGPT2 and EDN1 in vivo confirming the previous observation." (PMID 35513564, 2022).
tumor (continued). "During gastrin-induced migration, Fas-induced EMT and endothelin-1-mediated EMT and tumour invasion, the inactivation of GSK-3β by PI3k/Akt signalling promotes Snail expression and β-catenin stabilisation." (PMID 33239678, 2021). "The half-lives of angiogenic mRNAs, including ENG, EDN1, VEGFB and PDGFC, were reduced approximately 2-fold in Roquin2-overexpressing tumor cells compared to the control group." (PMID 34345214, 2021). "Among these, JMJD1A was found to regulate a subset of hypoxia-induced genes, ADM, EDN1, HMOX1, and GDF15, and was important for the growth of tumour xenografts in a hypoxic environment." (PMID 34572020, 2021). "SOX4 has been suggested to promote tumor angiogenesis through CXCR4 and endothelin-1 in breast and hepatocellular tumors, respectively, in 2 recent studies." (PMID 34228647, 2021). "Our present finding shows that Axl suppression of tumor cells by knockdown or BGB324 contributes to decreased secretion of factors known to promote angiogenesis, including thrombospondin-1, endothelin-1, uPA and VEGF." (PMID 31080559, 2019). "It has been reported that the ETA activation by its agonists (endothelin-1, ET1, and endothelin-2, ET2) promotes cancer progression through a network of cellular pathways and interactions with the tumor microenvironment." (PMID 30918259, 2019). "The endothelin-1 (ET-1) receptors (ET-1R) ETAR and ETBR, members of G-protein coupled receptors (GPCR) family, are well-known drivers of tumor progression in many human malignancies, including OC3." (PMID 31324767, 2019). "While this is in line with the observed strong reduction in ERK activation, it demonstrates that, although EDN1 is up‐regulated, antagonizing EDNR signalling can severely block tumour growth." (PMID 28606996, 2017). "The main functions of the top genes in OSPC2 network were associated to sensitization to chemotherapy (CXCR4, ANKRD1, CYR61, EDN1, ATP1B1, ARHGEF1, RTF1), and tumor suppression (FGFR3, BCL11B)." (PMID 28482906, 2017). "Vasoconstrictive endothelin-1 (ET1) and its receptor ETA via which ET-1 mediates vasoconstriction are both abundant in tumor tissues for maintaining the contractile tone of tumor vessels." (PMID 29311946, 2017). "The reduced ERK activity in BRAF inhibitor‐treated tumours correlated with increased MITF and EDN1 expression." (PMID 28606996, 2017). "Moreover, because the EDN1‐induced paracrine signalling has the potential to support both MITF‐high and AXL‐high phenotypes in acquired resistant tumours, targeting the EDN1‐EDN receptor axis could reduce the complexity seen in patients treated with MAPK inhibitor at time of progression." (PMID 28606996, 2017). "Endothelin-1 (ET-1) has nociceptive effects in the tumor microenvironment and it is highly secreted in OSCC and targeting ET-1 in pre-clinical models has shown to have anti-nociceptive effects." (PMID 27694791, 2016). "Several of these genes can also be considered as marker of tumor differentiation or contribute to epithelial-to-mesenchymal transition (EMT) such as CDH1, EDN1 or ERBB2 for instance." (PMID 27509260, 2016). "The anti-vascular effects of anakinra observed on histological sections were confirmed by gene expression analysis of Endothelin 1 and VEGF in tumours isolated from mouse tibiae." (PMID 27765923, 2016). "Consistently, after inhibiting miR-101, SH-SY5Y control cells showed down-regulation of the tumor suppressor EDN1 and CD44 genes, and increased expression of the tumor progression ENPP2 gene with respect to LMNA-KD cells transfected with the miR-101 mimic." (PMID 26439802, 2015). "To assess whether edn1 overexpression also causes similar effects, we analyzed the expression of lipogenic factors, lipogenic enzymes, the PPAR-γ targeting gene caveolin, cell cycle/division related genes, fibrosis and metastasis related genes, and tumor makers." (PMID 24416389, 2014).